MTOR (mechanistic target of rapamycin kinase)
Diseases named in the same sentence as MTOR in open-access papers (continued):
Sharing a sentence is not in itself a finding about the gene and the disease.
cancer (continued). "In addition to its general growth-like factor properties, S1P may act as a canonical activator of HIF-2α expression (via the Akt/mammalian target of rapamycin (mTOR) pathway), as it was shown in multiple cancer cell lines." (PMID 36631133, 2023). "Indeed, in the cancer setting mTOR plays a critical role in the regulation of tumor cell migration, invasion, and metastasis while previous studies have also highlighted a key role for mTOR in endothelial cell, vascular smooth muscle cell, macrophages and granulocyte migration." (PMID 36817783, 2023). "The PI3K/AKT/mTOR signaling pathway could regulate apoptosis and autophagy in cancer cells." (PMID 37558664, 2023). "The PI3K/Akt/mTOR pathway regulates cell proliferation, growth, cell size, metabolism, and motility, of which component genes have been extensively studied and found to be commonly activated in human cancer and inhibition of this pathway has been shown to lead to regression of human tumors." (PMID 37061713, 2023). "Compounds such as BEZ23518, which inhibit both PI 3-kinase and mTOR (which are related enzymes), may be of utility in cancer therapy by virtue of their ability both to inhibit two oncogenic pathways and to prevent the consequences of mTOR inhibitor-induced activation of PI 3-kinase/Akt signalling." (PMID 37143925, 2023). "PI3K/Akt/mTOR signals, promoted by point mutations of PI3K and Akt and by inactivity of the phosphatase and tensin homolog (PTEN), play an important role in the regulation of the proliferation and apoptosis of cancer cells, especially from ovarian, gastric and breast neoplasms." (PMID 37240821, 2023). "Furthermore, preliminary data from our laboratory indicate that this drug combination is also synergistic in other tumor entities in vitro, suggesting that cancer cells might be highly vulnerable to eIF4A and mTOR pathway inhibition." (PMID 36768380, 2023). "Finally, preclinical data suggest that combining MRTX1133 with EGFR or PI3K/AKT/mTOR pathway inhibitors may be synergistic in treating cancer." (PMID 37569406, 2023). "Therefore, targeting NUAK1 or combined inhibition with Akt or mTOR inhibitors may be considered in cancer treatments." (PMID 38135881, 2023). "However, the clinical efficiency should be evaluated considering the participation of mTOR and other crucial players whose perpetual activation could control cell growth and cancer cell metabolism." (PMID 37834467, 2023). "A recent trial of the mTOR inhibitor, everolimus, in combination with cisplatin given preoperatively to TNBC patients with residual disease following preoperative anthracycline/taxane showed responses to therapy in patients whose cancers had a PIK3CA mutation or a germline PALB2 mutation." (PMID 37491309, 2023). "Therefore, high levels of cholesterol may facilitate cancer cell proliferation through the upregulation of the PI3K/mTOR pathway in ovarian cancer." (PMID 37754524, 2023). "Similarly, fucoidan suppressed the phosphorylation of the PI3K/AKT pathway, which further downregulated the phosphorylation of the mTOR signaling pathway in HT-29 colon cancer cells, consequently leading to the suppression of the migration, invasion, and proliferation of cancer cells." (PMID 38248653, 2023). "Moreover, mTOR inhibitors can induce autophagy, which promotes cancer cell survival." (PMID 37834408, 2023). "Therefore, inhibition of the mTOR is beneficial in clinical settings for several types of cancers." (PMID 37046703, 2023). "Also, several mTOR-related drugs have been developed for the treatment of cancers before." (PMID 36959615, 2023). "In addition, a recent study has shown that in addition to mTOR inhibition, Ps could also block Wnt/β-catenin signaling pathway which contributes to the cancer initiation and progression." (PMID 36267272, 2022).
cancer (continued). "In addition, as a direct anti-tumor effect of metformin, AMP-activated protein kinase (AMPK) activation-mediated mTOR inhibition, the suppression of cancer stem cells, and the inhibition of cellular transformation are involved in the mechanisms of tumor suppression by metformin." (PMID 35740547, 2022). "Additionally, PLD1/2 has been reported to regulate several growth-related signaling pathways through its lipid product PA such as the mammalian target of rapamycin (mTOR) and the Hippo pathway, highlighting their crucial roles in growth control and cancer development." (PMID 35007762, 2022). "Therefore, we evaluated whether the cancer-promoting effects of NEIL3 in NSCLC are mediated by PI3K/AKT/mTOR signaling." (PMID 35535347, 2022). "In addition, genes in the PI3K/AKT/mTOR pathway change most frequently in human cancers." (PMID 35311154, 2022). "Given the observation that factor 1 was associated with IGF1R signaling and mTOR inhibitor treatment led to an increase in factor 1 scores, we hypothesized that mTOR inhibition leads to a reactive upregulation of IGF1R signaling in cancer organoids." (PMID 35668108, 2022). "Mitogen-activated protein kinase (MAPK) and PI3K-mammalian target of rapamycin (mTOR) signaling pathways play key functions in the regulation of cell survival, differentiation, proliferation, metabolism, and motility in response to extracellular stimuli and are deregulated in most cancers." (PMID 35513296, 2022). "In addition, elevated nuclear mTOR expression were observed in AA PCa and advanced cancer cells." (PMID 36077039, 2022). "Thus, unsurprisingly one of the first mTOR inhibitors had been tested against cancer." (PMID 36561137, 2022). "However, we found a number of established drivers of cancer progression and invasion (e.g., mTOR, STAT1/5, RHOC, ARF6, HMGB, and CRK) with increased expression levels as well as known suppressors (e.g., AIFL1 and SLIT3) with decreased expression levels upon PTEN inhibition." (PMID 36555834, 2022). "Moreover, several studies have confirmed that lncRNA Neat1 could sponge miR-185-5p to regulate IGF2 expression or DNMT1/mTOR signaling, promoting cancer progression." (PMID 35501920, 2022). "Moreover, the mTOR pathway plays a major role in the glucose metabolic program in cancers, and the alteration of glucose metabolism is one of the first identified hallmarks of cancer." (PMID 35557985, 2022). "In order to understand the molecular-level changes in cancer cells treated with lomitapide, we performed RNA-Seq analyses and found that lomitapide significantly impacted the autophagy-related genes, which supported the activation of autophagy by mTOR inhibition." (PMID 35831271, 2022). "The phosphatidylinositol-4,5-bisphosphate 3-kinase (PI3K)-Akt-mTOR pathway not only regulates the growth, proliferation, differentiation, and apoptosis of normal cells but also regulates the occurrence and development of cancer and its sensitivity to different therapies." (PMID 35280512, 2022). "Thus, it may be beneficial to administer compounds that enhance the stability of DEPTOR or its connection to mTOR, in an attempt to suppress mTOR and the growth, survival, and proliferation of cancer cells." (PMID 35078427, 2022). "Therefore, mTOR inhibitors are widely explored for cancer therapy." (PMID 35645799, 2022). "Moreover, inhibition of mTOR kinase may enhance the expression of PD-L1 on cancer cell surfaces, contributing to the reduced efficacy of mTOR inhibitors." (PMID 35682571, 2022). "However, the p-S6 protein has been used as a biomarker of the function of mTOR in human cancers." (PMID 35883491, 2022). "Therefore, PI3K/AKT/mTOR pathway has become a key therapeutic target for cancer treatment." (PMID 35311154, 2022). "In addition, PI3K/Akt regulates cancer cell growth by activating mTOR, which may promote cholesterol synthesis and uptake by activating SERBP." (PMID 35251975, 2022).
cancer (continued). "PI3K/Akt/mTOR pathway could be exploited or targeted for efficiently treating various cancers." (PMID 35774603, 2022). "Moreover, it is known that mTOR signaling may be crucial in defining the metabolic properties of cancer cells." (PMID 36287116, 2022). "However, inhibition of the PI3K/AKT/mTOR pathway could promote cancer cell death via different mechanisms." (PMID 35705657, 2022). "In addition, this analysis revealed the presence of several differentially expressed transcripts encoding key components of signal transduction cascades frequently found deregulated in several human cancers, including mTOR, KRAS, and TNF-α/NF-kB signaling pathways." (PMID 35918402, 2022). "This could lead to novel pathways in mTOR-resistant cancers." (PMID 35323341, 2022). "Dysregulation of PI3K/mTOR may result in cancer tumorigenesis." (PMID 36601056, 2022). "Especially, the PI3K/AKT/mTOR pathway was considered for bioinformatics evaluations, as this pathway modulates many aspects of cell biology, such as proliferation, survival and protein synthesis; all of which are known to be involved in the pathogenesis of cancer and fibrosis." (PMID 36344812, 2022). "Activation of Akt-mTOR signaling pathway has been reported to induce cancer cell resistance to ferroptosis through SREBP-1-mediated monounsaturated fatty acid production, whereas inhibition of this intracellular signaling can enhance the susceptibility of cancer cells to ferroptosis induction." (PMID 36431025, 2022). "Moreover, KEGG pathway analysis unveiled a potential association of 5′-tiRNA-ProTGG target genes with key oncogenic pathways, including AMPK signaling pathway, MAPK signaling pathway, MTOR signaling pathway and PD-L1 expression and PD-1 checkpoint pathway in cancer." (PMID 35625858, 2022). "Further pathway enrichment showed that miR-181a-5p and miR-125b-2-3p could regulate several biological pathways that were closely related to placental function, including the FoxO signaling pathway, focal adhesion, mTOR signaling pathway, and central carbon metabolism in cancer." (PMID 36188428, 2022). "Also, molecular alterations involving the mTOR pathway have been reported in a number of cancer types, which may limit the implications of the model’s predictions to cancers." (PMID 35078427, 2022). "Previous studies have shown that numerous natural substances have the ability to inhibit the PI3K/AKT/mTOR signaling pathway in a variety of cancer cells, which is considered to be an key effective strategy for cancer inhibition and has become a popular target for new cancer drugs." (PMID 35774597, 2022). "Hence, using prodigiosin as an effective mTOR inhibitor in different cancer types in vitro and in vivo might explain why mTOR inhibition effects PD-L1 expression levels differently." (PMID 36577970, 2022). "At the same time, both PD-1/PD-L1 monoclonal antibodies and PI3K/AKT/mTOR pathway inhibitors may develop resistance through activation of the bypass pathway, and have drug toxicity and side effects when achieving significant cancer suppression." (PMID 36313041, 2022). "Therefore lupeol may exert good anti- cancer activity by modulating the PI3k, mTOR and PTK signalling pathway." (PMID 36518133, 2022).
cancer (continued). "The PI3K/Akt/mTOR pathway is an important regulatory pathway for physiological activities such as cell proliferation, cell cycle, and apoptosis, and the hyperactivation of this signaling pathway plays an important role in cancer progression and cancer drug resistance." (PMID 35684449, 2022). "Consequently, we assessed if the modulation of mTor protein and its gene expression in 2D and 3D cultures for both cancer models might explain the differences in the response to everolimus." (PMID 35163092, 2022). "Upstream molecular switches, including receptor tyrosine kinases and Ras regulate several positive regulators like PI3K, AKT, mTOR, and eIF4E, which are abnormally activated in many tumorigenesis processes and are involved in controlling the survival, proliferation, and migration of cancer cells." (PMID 35313850, 2022). "However, the mTOR was frequently deregulated in human cancers." (PMID 36193308, 2022). "Together, these results suggest that PROX1 plays a critical role in the anti-proliferative effect of rapamycin on HCC and that the upregulation of PROX1 by an MTOR inhibitor might be a useful molecular marker for predicting the efficacy of its anti-cancer effect on HCC cells." (PMID 35159256, 2022). "Thus, these mutations may play a role in resistance of a subset of BRAF mutated cancers to targeted therapies, through the extensive crosstalk of the KRAS/RAF/MEK/ERK and the PI3K/AKT/mTOR pathways." (PMID 36079062, 2022). "Furthermore, via activation of mTOR (mammalian target of rapamycin) and subsequent phosphorylation of 4EBP1 (eukaryotic translation initiation factor 4E binding protein 1), c-Myc increases protein synthesis in cancers." (PMID 35884563, 2022). "Besides, m6A modifications frequently involve key components of oncogenic signaling pathways, including WNT/β-catenin, phosphatidylinositol-3-kinase (PI3K)/Akt and mammalian target of rapamycin (mTOR) signaling pathways, thereby contributing to their aberrant activation in cancer." (PMID 35884552, 2022). "The phosphatidylinositol 3-kinase/protein kinase B/mammalian target of the rapamycin (PI3K/AKT/mTOR) signaling pathway has been shown to be involved in essential cellular functions, including cell proliferation, differentiation, metabolism, survival, cancer and insulin resistance." (PMID 35327652, 2022). "Furthermore, BC18 and descendant cells had mutations in the cancer-related genes (in PDE4DIP, as well as a back mutation in MTOR, and USP6) in comparison to normal cells, which may have contributed to turning this lineage into an active cancer line." (PMID 35951662, 2022). "In addition, disrupted cellular signaling pathways in cancer patients (e.g., of the mechanistic target of rapamycin [mTOR]) may be controlled by the circadian clock, and thus may also underlie CTRS." (PMID 36387255, 2022). "We speculate that CCND1 gene amplification activates metabolism signaling pathways, such as the enhanced oxidative metabolism in cancer cells promotes activation of PI3K-Akt-mTOR signal axis, and then constructs an immune barrier of tumor microenvironment, resulting in resistance to ICIs therapies." (PMID 35844619, 2022). "Interestingly, mTOR activation is antitumoral in hypoxic TAMs but protumoral in cancer cells." (PMID 35242705, 2022). "Thus deregulation of mTOR leads to tumor growth and metastasis.The Akt (serine/threonine kinase) is a central node of many signaling pathways and it is often deregulated in most of the cancers." (PMID 36518133, 2022). "The proinflammatory cytokine IL-6 is commonly upregulated in various types of cancer including OSCC 44, and the elevated IL-6 level may promote nodal and distant metastasis by activating the PI3K/AKT/mTOR signaling pathway and correlate with cancer proliferation and poor survival." (PMID 36046647, 2022). "Furthermore, the mTOR pathway is often involved in resistance to cancer therapies." (PMID 35490242, 2022).
cancer (continued). "Moreover, ROS activates PIK3/AKT/mTOR signaling in the pathogenesis of cancer development." (PMID 36014933, 2022). "Thus, our approach of specific MYCN targeting by BGA002 may result in the inhibition of the mTOR pathway only in cancer cells, leaving healthy cells unaffected." (PMID 35490242, 2022). "GSEA showed that the pathway of PI3K/AKT/mTOR, G2/M checkpoints, and E2F target were abnormally activated in NEIL3 patients while western blot revealed that NEIL3 could partially activate the PI3K/AKT/mTOR signaling pathway, which might be responsible for the cancer-promoting effects of NEIL3." (PMID 35535347, 2022). "Moreover, the levels of p-AKT and p -mTOR were lower in AGS cells than in control cancer cells." (PMID 35186488, 2022). "Furthermore, mTOR controls fatty acid oxidation and provides substrates to generate energy through the TCA cycle and oxidative phosphorylation and meet the nutritional demands of cancer cells during glucose deficiency." (PMID 35745875, 2022). "Significantly, the upregulated MP genes were enriched, while the downregulated MP genes were depleted in the transcriptomes of residual tumors, suggesting that the mTOR-regulated persister state may be responsible for the minimal residual disease phenotype following clinical cancer chemotherapy." (PMID 36396656, 2022). "Interestingly, we confirmed our hypothesis and showed that GOLPH3 inhibited Akt phosphorylation at Ser473; this contradicts the majority of previous studies, which reported that GOLPH3 activates the Akt/mTOR signaling to accelerate cancer progression." (PMID 35190555, 2022). "Therefore, the mTOR signaling system could be suggested as a cancer biomarker, and its targeting is important in anti-tumor therapy research." (PMID 36428613, 2022). "The mechanistic/mammalian target of rapamycin (mTOR) is a Serine/Threonine kinase, that plays a central role in regulating human physiological activities including tissue regeneration, regulatory T cell differentiation, and function, and various types of cancers." (PMID 36590916, 2022). "Therefore, how to overcome resistance to mTOR inhibitors in the future, as well as actively target the mTOR pathway using metabolic disturbances in cancer cells, may be of great help in the treatment of CRCs." (PMID 36778600, 2022). "Previous studies have shown that the PI3K/AKT/mTOR signalling pathway plays a key role in the survival and growth of tumour cells, so it might become an ideal intervention target for cancer treatment, resulting in the birth of many small molecule targeted drugs." (PMID 35165269, 2022). "Thus, the Rheb/mTOR signaling plays an important role in cancer development." (PMID 36180910, 2022). "Finally, the combination of RAD001 and Rhein significantly decreased tumor weight and volume, suppressed the expressions of p-PI3K, p-Akt and p-mTOR, and repressed cell proliferation marker Ki-67 expression, which exerted synergistic cancer prevention in GC in vivo." (PMID 35209807, 2022). "As numerous cancer treatments aim at reducing Akt–mTOR activity in the tumour, we wondered if this systemic reduction in Akt–mTORC1 signalling could have adverse effects on skeletal muscle during cancer cachexia, possibly by reducing mTORC1 signalling even further." (PMID 34741441, 2022). "Thus, mTOR inhibitors have been developed for cancer therapy." (PMID 34760363, 2021). "Furthermore, animal-based models have shown that these molecules affect the activity of various enzymes and signaling pathways, such as MAPK, PI3K/Akt/mTOR, JAK/STAT, and NF-κB, acting as the underlying mechanisms of their reported anti-inflammatory, neuroprotective, and anti-cancer effects." (PMID 33919211, 2021).